IFNAR1 (interferon alpha and beta receptor subunit 1)
Diseases named in the same sentence as IFNAR1 in open-access papers (continued):
Sharing a sentence is not in itself a finding about the gene and the disease.
influenza (continued). "In the current study, we adopted the influenza infection model and found that Ifnar1−/− mice undergo more acute and severe inflammation than B6 wild-type (WT) mice." (PMID 21383977, 2011). "Collectively, these results demonstrate that disruption of IFNAR1-mediated signaling substantially impairs the host antiviral response, leading to enhanced replication of multiple influenza virus subtypes, including both influenza A and B lineages." (PMID 40872812, 2025). "It is intriguing that the known patients with AR IFNAR1 or IFNAR2 deficiency did not suffer from critical influenza." (PMID 36112363, 2022). "Overall, greater Proteobacteria colonization levels after influenza infection in WT mice were not caused by differences in Proteobacteria abundance between WT and Ifnar1-/- mice prior to PR8 infection." (PMID 27149619, 2016). "Conversely, increased susceptibility of C57BL/6 IFNAR1−/− mice to influenza infection results from severe lung inflammation rather than defective viral clearance." (PMID 25500584, 2014). "Both AM and neutrophils in the lung seemed identical in WT and Ifnar1−/− mice except that some neutrophils from Ifnar1−/− mice exhibited larger size and had a more diffused nucleus, but monocytes were clearly different in the lung of WT and Ifnar1−/− mice after influenza infection." (PMID 21383977, 2011). "WT and IFNAR1-KO MDCK cells were infected with representative strains of influenza A (H1N1 and H3N2) and influenza B (B/Victoria)." (PMID 40872812, 2025). "Influenza infection leads to drastically elevated CCL2 concentration in the lungs of both young and aged mice, and anti‐IFNAR1 treatment repressed lung CCL2 concentrations in both young and aged mice." (PMID 34547174, 2021). "Unexpectedly, one of these variants has been reported in patients with life-threatening influenza pneumonia (TLR3 p.Pro554Ser) and another was shown to be both deleterious and dominant-negative (IFNAR1 p.Pro335del)." (PMID 32972995, 2020). "In the case of influenza and its tissue tropism for airway epithelia, IFN-λ-mediated protection is enough to halt influenza replication and spread in this tissue expressing the IFN-λR, which explains the often mild influenza phenotype of Ifnar1−/− mice." (PMID 25714109, 2015). "However, studies performed in IFNAR1−/−, IL-28Rα−/−, and IFNAR1/IL-28Rα double knockout mice show that, in primary airway epithelia, upon influenza infection, IFN-I and IFN-III mediate parallel amplification loops that lead to the induction of fully overlapping groups of ISGs." (PMID 28184222, 2017). "While there were differences between S. Typhimurium-only infected WT and Ifnar1-/- mice, these differences were strongly exacerbated when mice were previously infected with PR8, indicating the contribution of IFN-Is produced during influenza infection to secondary S. Typhimurium infection." (PMID 27149619, 2016). "In order to investigate the role of IFN-Is induced during influenza infection in modulating the endogenous intestinal microbiota, we established a model of influenza pulmonary infection using genetically modified animals with defective IFNAR signaling (Ifnar1–/–mice)." (PMID 27149619, 2016). "Considering that the number of S. Typhimurium that disseminated systemically was greatly increased following influenza infection in WT, but not in Ifnar1-/- mice, this suggests that IFN-Is may potentially relax the intestinal barrier to allow for Salmonella systemic dissemination." (PMID 27149619, 2016). "The transcriptional response to influenza infection was largely dependent on IFNs, as it was reduced to a few upregulated genes in epithelia lacking receptors for both type I and III IFN (IFNAR1−/−IL-28Rα−/−)." (PMID 24278020, 2013).
influenza (continued). "Neither IFNα nor influenza infection were able to stimulate Mx or PKR in the biallelic chIfnar1−/−, which is in agreement with the observation in mammals, indicating that activation of Mx and PKR in chickens is stimulated by Type I IFNs through activation of the Type I IFN receptor IFNAR1." (PMID 35056582, 2022). "Similarly, treatment with IFNAR1 blocking antibody (αIFNAR1) in BLM-pretreated mice infected with sub-lethal doses of A/PR8 showed reduced body weight for 7 days, suggesting that BLM treatment did not inhibit influenza infection." (PMID 34484196, 2021).
colitis (19 papers, 2011 to 2025). Inflammation of the colon. "In this study, we found that type I IFN signaling is pathogenic in S. typhimurium-induced colitis, with wild-type (WT) mice dying faster than Ifnar1-/- mice." (PMID 29190678, 2017). "Using this model, loss of Ifnar1 in IECs was reported to increase inflammation and severity of colitis." (PMID 28428788, 2017). "Our IFNAR1 expression data identifies a correlation between the loss/downregulation of IFNAR1 on DCs and exacerbation of colitis." (PMID 21365015, 2011). "The susceptibility of IFNAR1−/− mice to DSS-induced colitis suggests that the expression of this receptor is important in protection against gut inflammation." (PMID 21365015, 2011). "Based on the observed increase in IL-10R expressing CD11c- macrophages and CD103+ cDCs in S. typhimurium infected Ifnar1-/- mice compared to WT mice, we sought to investigate the role of IL-10R in the reduced susceptibility of these mice to S. typhimurium colitis." (PMID 29190678, 2017). "Indeed, blockade of IL-10R in Ifnar1-/- mice resulted in increased susceptibility to S. typhimurium colitis, eliminating the difference in mortality compared to WT mice." (PMID 29190678, 2017). "Additionally, Ifnar1 loss in myeloid cells promoted colitis via increased IL-1 production, a pro-inflammatory cytokine produced by activated macrophages." (PMID 28428788, 2017). "Furthermore, mice with IFNAR1 deletion specifically in myeloid cells demonstrated significantly increased weight loss and colitis disease activity score when treated with DSS." (PMID 25309533, 2014). "Additionally, as we and others have shown, IFNAR1−/− mice are more susceptible to DSS-induced colitis." (PMID 21365015, 2011). "It has been reported that IFNAR1−/− mice have increased susceptibility to DSS-induced colitis." (PMID 21365015, 2011). "This corroborates the previous finding that Ifnar1-/- mice are more susceptible to colitis and that IFN-β production triggered by double-stranded RNA of a commensal microbe protect mice from colitis." (PMID 37215126, 2023). "Histology also showed exacerbation of colitis in anti-IFNAR1 treated mice compared with that in control mice." (PMID 36268010, 2022). "Ifnar1−/−-recipient mice developed severe colitis, compared with Ifnar1+/+ mice, when inoculated with CD4+ T cells from a WT mouse." (PMID 28428788, 2017). "In a T cell adoptive transfer model of colitis, signaling through host hematopoietic cell Ifnar1 was necessary to deter development of colitis." (PMID 28428788, 2017). "In our colitis model, WT and Ifnar1-/- mice were treated with streptomycin 1 day prior to S. Typhimurium infection in order to achieve acute inflammation of the cecal mucosa." (PMID 27149619, 2016). "The functional changes in DCs combined with an altered intestinal Treg profile in the PPs of IFNAR1−/− mice and an increased sensitivity to colitis suggest a role for Type I IFN signaling in controlling intestinal inflammation and homeostasis." (PMID 21365015, 2011). "In the acute experimental colitis model induced by dextran sulfate sodium (DSS), the deletion of the Ifnar1 would exacerbate the disease progression, whereas administration of recombinant type I interferon exerts protective effects against colitis through acting on myeloid cells." (PMID 41359111, 2025). "Blocking of IFNAR1 reduced AREG-expressing ILC2s in WT and Rag2-deficient mice, which have been reported to play critical roles in DSS-induced colitis." (PMID 36268010, 2022). "However, the severity of colitis induced by Ifnar1−/−Ifngr1−/− T cells was reduced compared to WT T cells, which correlated with a reduced rate of expansion of Ifnar1−/−Ifngr1−/− T cells in the blood." (PMID 30796216, 2019). "Thus, although a correlation between downregulation of IFNAR1 on DCs and exacerbation of colitis was observed, pretreatment of colitic mice with La-IFN-β surprisingly also resulted in increased intestinal damage." (PMID 28352268, 2017).
colitis (continued). "Furthermore, it shows that from just after bacterial treatment through the course of colitis, the IFNAR1 expression remained significantly lower on the CD103+ DCs in the PPs in the La-IFN-β mice than in the other groups." (PMID 21365015, 2011). "Likewise, IFNAR1−/− mice display an increased sensitivity to dextran sulfate sodium (DSS)-induced colitis, suggesting Type I IFN play a protective role during inflammation of the gut." (PMID 21365015, 2011). "Examination of IFNAR1 expression on CD103+ DCs from the treatment groups in our colitis model revealed that there was a reduction in receptor expression in mice pretreated with La-IFN-β in all of the intestinal tissues we examined, with the most significant reduction occurring in the PPs." (PMID 21365015, 2011). "The decrease of IFNAR1 surface expression prior to induction of colitis may have inadvertently led to the inability of IFN-β to signal during the inflammatory period." (PMID 21365015, 2011). "To analyze the effects of T1IFN signaling on ILC2s during colitis, we blocked T1IFN signaling in mice by i.p. injecting anti-IFNAR1 antibody to mice on day 0 and administered DSS." (PMID 36268010, 2022). "Flow cytometric analysis of macrophages and conventional dendritic cells (cDCs) during active colitis demonstrated an increase in CD11c- macrophages and CD103+ cDCs in the colon of Ifnar1-/- animals." (PMID 29190678, 2017). "Blockade of either TLR9 signaling or IFNAR1 inhibits the protective capability of TLR9 agonists, such as probiotics, in murine colitis." (PMID 21365015, 2011). "Interestingly, the authors further showed that IFNAR1−/− mice recovered from DSS treatment more quickly than wild-type mice, suggesting a deleterious role of type I IFNs during the recovery phase of colitis." (PMID 25309533, 2014). "However, a later study found that deletion of Ifnar1 in LysM+ myeloid cells, but not in conventional DCs exacerbated DSS-induced colitis." (PMID 28428788, 2017).
Sepsis (16 papers, 2011 to 2025). Sepsis is defined as life-threatening organ dysfunction caused by a dysregulated host response to infection. "Wild type (WT) mice treated with poly(I:C) exhibited altered expression patterns of TNF and IL-12p40 during CASP which were dependent on IFNβ or IFNAR1, suggesting a mechanism for the increased sepsis susceptibility of WT mice." (PMID 31500303, 2019). "Using the colon ascendens stent peritonitis (CASP) model, we demonstrate that IFNβ−/− and type I IFN receptor (IFNAR1)−/− mice were less susceptible to sepsis after pre-stimulation with the viral mimetic poly(I:C)." (PMID 31500303, 2019). "Ifnb−/− and Ifnar1−/− mice are more susceptible to Streptococcal infection, although Ifnar1−/− mice are protected from infection by Listeria, Chlamydia and in polymicrobial sepsis." (PMID 21755013, 2011). "To determine if IFNβ plays a functional and non-redundant role in the susceptibility to systemic bacterial infections we performed CASP surgery as an experimental sepsis model and monitored survival in IFNβ−/−, IFNAR1−/− and WT mice." (PMID 31500303, 2019). "For example, IFNAR1 mice have shown both increased resistance and sensitivity to polymicrobial sepsis." (PMID 30319651, 2018). "Since Ifnar1−/− mice exhibit similar fungal burdens in critical organs when compared to WT animals, the sepsis resistance phenotype may result from increased host tolerance to the pathogen burden." (PMID 22911155, 2012). "The volcano plot and heatmap indicated that JAK3, CHMP5 and IFNAR1 were upregulated while CASP8, VDAC2, FASLG, JAK1, STAT4 and BCL2 were downregulated in sepsis." (PMID 38894720, 2024). "Treatment of wild-type mice with an anti-IFNAR1 antibody, or deletion of IFNAR, protected mice from LPS-induced lethality and CLP-induced sepsis." (PMID 36899914, 2023). "To elucidate the mechanisms underlying the reduction in mortality rates during polymicrobial sepsis in IFNβ−/− and IFNAR1−/− mice in the presence vs. absence of a poly(I:C) pre-stimulation, we analyzed the antibacterial host response in the mouse strains." (PMID 31500303, 2019). "In our study direct comparisons between WT, IFNβ−/− and IFNAR1−/− mice indicated that poly(I:C)-induced IFNβ production has a non-redundant, detrimental role in IFNAR-mediated sensitization leading to increased mortality rates early during polymicrobial sepsis." (PMID 31500303, 2019). "Another possible interpretation is that IFNβ, in contrast to all other IFNα isoforms, have a unique non-Jak/STAT pathological signaling feature through IFNAR1, independent of IFNAR2 (the high affinity receptor for IFNα/β) as reported in a model of LPS-induced sepsis." (PMID 27792766, 2016).
Autoimmunity (15 papers, 2009 to 2025). The occurrence of an immune reaction against the organism's own cells or tissues. "While IEI have been thought to be rare, common single‐nucleotide polymorphisms (SNPs) have also been found in TYK2 and IFNAR1 and are associated with improved protection from infection as well as increased risk of autoimmunity." (PMID 36929731, 2023). "It will therefore be critical to assess the function of TAM receptors and the differential roles of IFNAR1 and IFNAR2 in the development of autoimmunity." (PMID 19624844, 2009). "We hypothesize that the lack of negative regulatory molecule function in IFNAR1-/- mice may result in phenotypic differences between IFNAR1-/- and IFNAR2-/- mice in models of autoimmunity." (PMID 19624844, 2009).
breast carcinoma (15 papers, 2013 to 2024). "Higher IFNAR1 expression was associated with lower survival in breast cancer patients and patients with other cancer types including lung squamous cell carcinoma and pancreatic adenocarcinoma." (PMID 38638003, 2024). "Loss of functional IFNAR1 not only resulted in earlier onset and increased tumor multiplicity, but also in the presentation of a gene expression profile associated with aggressive human breast cancer." (PMID 32296435, 2020). "In both breast cancer cell lines, anti-IFNAR1 antibody completely blocked 4HC induction of Igtp, but only partially inhibited the induction of Oasl1 and Cxcl10." (PMID 36187936, 2022). "Taken together, these data indicate that the type I IFNs/IFNAR1/STAT1 pathway plays a critical role in mediating ISG upregulation in breast cancer cells in response to genotoxic treatment." (PMID 27791205, 2016). "Studies also have demonstrated that loss of IFNAR1 expression and JAK/STAT signaling may reduce NK cell-mediated antitumor immunity and thus promote breast cancer metastasis." (PMID 36612165, 2022). "Thus, in summary for both cohorts of MZ twins and breast cancer patients, Illumina SNP beadchips suggested a post-zygotic mosaicism in 41 out of 84 (48.8%) cases, in the locus between IL10Rβ and IFNAR1 genes represented by the four consecutive array probes." (PMID 24023707, 2013). "Finally, the growth control of M/D-driven mammary carcinomas by radiotherapy could be enhanced by venetoclax, and this improvement was abolished upon neutralization of IFNAR1." (PMID 37623817, 2023). "We compared IFNAR1 expression on the surface of PMN and Mon from healthy donors and patients with non-small cell lung cancer, pancreatic cancer, breast cancer, head and neck cancer, and colon cancer." (PMID 33741967, 2021). "Moreover, in mouse mammary cancer cells, expression of an IFNAR1 mutant that is resistant to degradation did not alter the proliferation of these cells in vitro or when implanted subcutaneously in syngeneic mice but did increase tumor growth when implanted orthotopically into mammary glands." (PMID 33801234, 2021).
malaria (15 papers, 2010 to 2026). Malaria is a serious and sometimes fatal disease caused by a parasite that commonly infects a certain type of mosquito which feeds on humans. "The impact of each genetic variant on IFNAR1 expression and function still need to be determined, but these findings suggest that type I IFNs are important regulators of malaria disease in humans." (PMID 33408718, 2020). "Accordingly, several studies identified Type 1 Interferon Receptor 1 (IFNAR1) gene polymorphisms associated with mild malaria, disease severity and cerebral malaria in children." (PMID 31417551, 2019). "Importantly, genetic variants in IFNAR1 have been associated with either greater or lower risk of severe malaria disease." (PMID 33408718, 2020). "Interestingly, IFNAR1 SNP alleles that are associated with CM resilience also show to confer increased risk of mild malaria development." (PMID 31417551, 2019). "Polymorphisms in the Ifnar1 gene have been associated with reduced risk of severe malaria." (PMID 27812214, 2016). "Since oxidative stress is linked to malaria severity, this may explain the improved clinical symptoms observed when IFNAR1 is deficient or blocked in mice and the link of specific SNPs in IFNAR1 to cerebral malaria resistance in patients." (PMID 31265218, 2019). "Here, we used an experimental genetic heterogenic system where homozygous primigravid mice carry heterozygous fetuses, aiming to discern whether the expression of TLR4 and IFNAR1 molecules in either maternal or fetal compartments is implicated in outcomes of malaria in pregnancy." (PMID 29440369, 2018). "We found that BECs from IFNAR1 and IFNb KO mice show reduced efficiency in presenting malaria antigens." (PMID 36993973, 2023). "Medium supplementation with IFNβ rescued antigen presentation efficiency of IFNB KO BECs, indicating that Type I IFN signaling through IFNAR1 is a determinant of malaria antigen presentation by BECs." (PMID 36993973, 2023). "We revisited genetic evidence provided by inflammatory response genes that have been repeatedly associated to malaria, namely TNF, NOS2, IFNAR1, HMOX1, TLRs, CD36, and CD40LG." (PMID 31417551, 2019). "The involvement of IFNAR1 in innate and adaptive responses to malaria parasites warrants the evaluation of the contributions of maternal and fetal IFNAR1 to MiP pathogenesis." (PMID 29440369, 2018). "We have investigated the role of TLR4 and IFNAR1 in malaria during pregnancy, with a focus on dissecting the contributions of maternal and fetal compartments to pregnancy outcomes." (PMID 29440369, 2018). "Our previous studies using a lethal model of malaria demonstrated that IFNAR1- signalling occurred via cDC, which resulted in potent suppression of Th1-immunity, and was associated with effects on PDL1, PDL2 and IL-10 expression by cDC subsets." (PMID 27812214, 2016). "While WT mice succumbed 5–8 d post infection, the majority of Ifnar1-/- mice survived (~80%) and controlled parasite growth, as was also reported for Ifnar1-/- mice inoculated with the P. berghei ANKA mouse model of severe malaria." (PMID 27792766, 2016). "Our demonstration that IFNAR1-signalling restricts the onset of humoral immunity to malaria is the first description of cytokine-mediated suppression of Tfh, GC B-cell and plasmablast formation during parasitic infection." (PMID 27812214, 2016). "The aim of this paper was to determine the effect of IFNAR1-signalling on humoral immune responses during experimental malaria." (PMID 27812214, 2016). "Given a recent report that PDL2-signalling can compete against the regulatory effects of PDL1, and indeed, can protect against experimental malaria, we speculate that IFNAR1-signalling in cDC regulates CD4+ T cell activation by favouring PDL1-signalling over protective PDL2 signals." (PMID 27812214, 2016). "Previous studies correlated genetic variations of IFNAR1 in African children and ECM models with protection from severe malaria." (PMID 34659202, 2021).